ICAM1 (intercellular adhesion molecule 1)
Diseases named in the same sentence as ICAM1 in open-access papers (continued):
Sharing a sentence is not in itself a finding about the gene and the disease.
tumor (continued). "Other tumor cells express integrin α4β1, mediating direct binding between tumor cells, bone matrix cells, and vascular cells through intercellular adhesion molecule-1 (ICAM-1) and vascular cell adhesion molecule 1 (VCAM-1)." (PMID 38243240, 2024). "In vivo mouse models with GC receiving high-dose ICAM-1 CAR-T therapy showed a reduction in tumor burden, with some achieving complete eradication." (PMID 39397869, 2024). "Antibody specifically blocking ICAM-1‒FGG interaction significantly suppressed NSCLC tumor growth in a mouse xenograft model." (PMID 39168965, 2024). "CLEVER-1 promotes CD4+ FoxP3+ Tregs transmigration through ICAM-1 and vascular-associated protein-1 (VAP-1) and further infiltration within the tumor niche." (PMID 39596815, 2024). "This process involves β2 integrins on neutrophils and intercellular adhesion molecule-1 on tumor cells, which stabilize the tumor cells and enhance their spread to the lungs." (PMID 38760815, 2024). "ICAM1 was expressed on the surface of cells with features such as chemoresistance, stemness marker expression, and tumor-initiating behavior." (PMID 39201551, 2024). "More importantly, their tumor cell-killing ability was significantly enhanced, indicating a positive impact of Icam1 inactivation on T cell effector function." (PMID 38490212, 2024). "In another study, single‐cell RNA sequencing of mice with mammary tumours identified ICAM1 as a driver of breast cancer lung metastasis, and ICAM1‐ICAM1 homophilic interactions promoted the aggregation and adhesion of CTCs to tumour endothelial cells." (PMID 39350478, 2024). "High ICAM-1 expression is sensitive to drugs targeting tumor cell proliferation, apoptosis, and angiogenesis." (PMID 38799250, 2024). "Atorvastatin effectively inhibited ICAM1 expression in tumor cells, and tumor cells with ICAM1 knockout or treated with atorvastatin were unresponsive to neutrophil activation." (PMID 38907234, 2024). "In a CD20/EGFR CAR T cell model, ICAM-1 was shown to increase in an IFNγ dependent manner and permitted tumor islet infiltration by T cells." (PMID 38786066, 2024). "On the other hand, soluble ICAM-1 released by tumor cells inhibited NK functions in patients with colonic carcinoma, thus suggesting a mechanism of tumor immune escape." (PMID 39596815, 2024). "To investigate the role of tumor cell ICAM1, we established stable shICAM1 cell lines, specifically the 4T1-shICAM1-2 and MDA-MB-231-shICAM1-2 cell lines, for subsequent experiments." (PMID 38907234, 2024). "GRHL2 was previously shown to support NK cell-mediated tumor cytotoxicity through a mechanism involving epigenetic stimulation of ICAM-1 expression, which supported enhanced NK-target cell synapse formation." (PMID 38706844, 2024). "It is well-known that ICAM-1 plays a crucial role in mediating cancer cell migration and spreading, however little is known about tumorous ICAM-1 intrinsic effects with regards to cancer cell survival and tumor progression." (PMID 39168965, 2024). "Initially, CAR-T cell activation strongly depends on the expression level of ICAM-1 on tumor cells, where CAR-T cells detach from malignant cells more quickly than normal T cells due to LFA-1 downregulation in the IS." (PMID 38779672, 2024). "That indicates that the expression of ICAM-1 in tumor cells plays an important role in their adhesion and transmigration." (PMID 38892286, 2024). "Tumor cells, especially CTCs and cancer cells in early metastasis, can acquire genetic alterations to express ICAM-1 and VCAM-1, which enable both attraction and retention of myeloid cells." (PMID 38786066, 2024). "We next chose luciferase‐transfected A375 cells (A375‐luc), which has moderate‐low expression of ICAM1, to construct an orthotopic xenograft tumor model to further confirm the anti‐tumor and anti‐metastatic efficacy of I1‐DXd monotherapy or combined with DAC." (PMID 38874532, 2024).
tumor (continued). "The study found that ICAM-1-targeted NIR-PIT significantly inhibited tumour growth and prolonged survival using a human TNBC xenograft mouse model." (PMID 39498336, 2024). "In cancer, ICAM-1 has been shown to play a role in recruiting integrin β2-expressing immune cells from bloodstream to ICAM-1–expressing tumor, thus initiating cancer-related immune responses throughout oncogenesis." (PMID 39168965, 2024). "Such new insights should inspire further dissection of these ICAM-1-dependent interactions in the tumor context." (PMID 39596815, 2024). "The findings underscore the multifaceted role of ICAM1 in cancer biology, particularly regarding its influence on tumor immunity and the involvement of immune cell infiltration in the TME." (PMID 39767561, 2024). "Lymphocyte function adhesion molecule-1 (LFA-1) is responsible for the initial capture of neutrophils, whereas the interaction between tumor ICAM-1 and neutrophil MAC-1 is involved in maintaining clusters of neutrophils." (PMID 39035739, 2024). "ICAM1 plays a vital role in the interplay between tumor biology and immune response, presenting opportunities for novel therapeutic interventions and improved patient prognostication in various cancers." (PMID 39767561, 2024). "In melanoma, IL-8 produced by cancer tumor cells attracts neutrophils, that promotes by induction of MAC-1 and ICAM-1 the interaction between cancer tumor cells and neutrophil clusters, and the endothelium." (PMID 39035739, 2024). "It is reported that ICAM-1–MUC1 interaction reprograms cytokine and protease secretion in tumor milieu and induces ICAM-1 up-regulation in malignant cells, thus promoting tumor cell migration and metastasis." (PMID 39168965, 2024). "ICAM-1, -2 and -3 are expressed by both leukocytes and endothelial cells, although only bone marrow and tumour endothelial cells can express ICAM-3." (PMID 38391953, 2024). "Endothelin-1 (ET-1) is involved in reducing the expression of ICAM-1 on tumor endothelial cells and of tumor-infiltrating leukocytes." (PMID 39325128, 2024). "An increased level of VEGF inhibits the expression of intercellular adhesion molecule-1 (ICAM-1) and vascular cell adhesion molecule-1 (VCAM-1), thereby inhibiting the adhesion of tumor-associated endothelial cells to leukocytes." (PMID 39408814, 2024). "The accumulation of VEGF within the tumor inhibits ICAM-1 and VCAM-1 expression on endothelial cells, potentially impeding immune cell infiltration." (PMID 38541124, 2024). "Previous reports in solid tumors correlated high ICAM1 expression with worse prognosis and invasive potential of the tumor cells." (PMID 39034990, 2024). "The binding of CD11b to ICAM1 on tumor cells triggers activation of the MAPK pathway within tumor cells, leading to the upregulation of MMP9 expression." (PMID 38907234, 2024). "In contrast, aT-sEVs downregulated the expression of PD-L1, TAP1, HLA-A, HLA-B, HLA-C and ICAM-1 in tumour cells." (PMID 38719909, 2024). "This exploration is critical, as it not only enhances our understanding of ICAM1’s role in carcinogenesis but also its potential impact on tumor immunity." (PMID 39767561, 2024). "Tumor tissue staining demonstrated a significant reduction in neutrophils and ICAM1 within the tumors, accompanied by inhibited expression of the MAPK pathway and its downstream target MMP9." (PMID 38907234, 2024). "The results were further verified by flow cytometry, and IFN-γ treatment, in accordance with previous reports, upregulated the membrane expression of both MHC-I and ICAM-1 on tumour cells." (PMID 38719909, 2024). "For example, ICAM-1 can target near-infrared light immunotherapy (NIR-PIT) to inhibit tumor growth and improve the survival rate of TNBC patients." (PMID 38799250, 2024). "In tumor progression, abnormal microRNAs (miRNAs) are related to cancer cell mobility and migration and regulate ICAM-1 expression." (PMID 39132161, 2024).
tumor (continued). "Vascular endothelial cadherin (VE-cadherin) and intercellular adhesion molecule-1 (ICAM1) have been reported to promote tumor infiltration of CD8 T cells and favor their anti-tumor effects." (PMID 38332012, 2024). "Neutrophil-tumor cell binding was dependent on the molecular interaction of neutrophil Mac-1 integrin with tumor ICAM-1." (PMID 38786066, 2024). "Strikingly, patients having more ICAM-1-expressing circulating tumor cells (CTCs) showed shorter disease-free survival periods." (PMID 38786066, 2024). "We further investigated the upregulation of ICAM-1 among tumor-infiltrating cell subpopulations in tumors after RT plus VS-6063 treatment." (PMID 38169608, 2024). "N2-TANs have been reported to bind disseminated tumor cells via MAC-1/ICAM-1 and to facilitate their endothelial transmigration, thus favoring tumor metastasis." (PMID 38334604, 2024). "In non-tumor contexts, targeting ICAM1 (intercellular adhesion molecule 1) on HIV-1 viruses encapsulated in EVs can hinder their spread to T cells by preventing binding to the specific integrin FLA1." (PMID 39643909, 2024). "Our analysis of TNBC patient and mouse tumor sections revealed that neutrophils primarily localized around tumor cells exhibiting high ICAM1 expression." (PMID 38907234, 2024). "Several antigen presentation genes, such as Tap1 and CD74 and some regulators involved in tumor cell immunogenicity, such as Irf1, Icam1 and CD40 were also upregulated by Mi-2β knockout in vitro." (PMID 38461299, 2024). "The JAK‐STAT3 signalling pathway activated by GM‐CSF increased ICAM1 expression, that facilitated tumour metastasis through neovascularization." (PMID 39021279, 2024). "Hepatoma cells isolated from hepatocarcinoma (HCC) patients also included ICAM-1-positive subpopulations and those ICAM-1+ cells were greater at forming tumor spheres." (PMID 38786066, 2024). "The expression of Intercellular Adhesion Molecule-1 (ICAM-1), a transmembrane glycoprotein belonging to the immunoglobulin superfamily (IgSF), is observed in tumor cells." (PMID 38361933, 2024). "After transversing across stromal cells and ECM, CAR T-cells then can seek direct tumor contact via intracellular adhesion molecule-1 (ICAM1) and execute anti-tumor cytotoxicity." (PMID 39317919, 2024). "This is supported by our very recent finding that ICAM-1/LFA-1-mediated adhesion was essential for the interaction between tumour cell-derived PD-L1+ sEVs and T-cell PD-138." (PMID 38719909, 2024). "ICAM-1 also plays a key role in cell adhesion to endothelium and tumor development, as well as cell proliferation, invasion, and angiogenesis." (PMID 37875556, 2023). "ICAM1, a cell adhesion molecule, is highly expressed in vascular endothelial, epithelial, and immune cells in response to inflammation and tumor cell stimuli." (PMID 37131205, 2023). "This ICAM-1 upregulation permitted EGFR CAR-T cells to move from tumor edge to center, and blockade of ICAM-1/LFA-1 disrupted the CAR-T cell tumor infiltration." (PMID 36895477, 2023). "We found that ICAM-1+ tumor cells showed much higher binding ability with CD11b−/− neutrophils than ICAM-1− tumor cells." (PMID 37345070, 2023). "From the tumor side, ICAM-1 appears to be important for the physical interaction with CTL with little signaling function in this context." (PMID 37732732, 2023). "Taken together, these data suggest that ICAM-1 on tumor cells binds to CD11b on neutrophils, thereby promoting a firm binding of neutrophils with tumor cells." (PMID 37345070, 2023). "It is worth noting that CD8+ T cells tend to aggregate in the ICAM1-positive tumor areas, which were also observed in mice harboring orthotopic lung tumors." (PMID 36871040, 2023). "While ICAM-1 contributes to the formation of a productive immunological synapse leading to tumor killing, its absence or release of sICAM-1 inhibits tumor cell killing." (PMID 37732732, 2023).
tumor (continued). "In the current investigation, the disposition of V937 has been characterized in non-tumor-bearing Hu/Mu ICAM-1 transgenic mice developing a physiologically based pharmacokinetic model." (PMID 37771727, 2023). "These genes, including IL6, ICAM-1, and CXCL14, are associated with immune cell signaling, tumor progression, and metastasis, indicating that tumor cells induce a highly specific gene expression signature to enforce their tumorigenic properties in the TME." (PMID 36868311, 2023). "Tumor endothelial cells act as a major barrier for the extravasation of effector T lymphocytes into the tumor niche through the downregulation of ICAM1 and VCAM1." (PMID 37056346, 2023). "We examined ICAM1’s role in TNBC, focusing on its expression, cell survival, mutation, and tumor immunity." (PMID 37671167, 2023). "Together, these data indicate that ICAM‐1 in cancer cells contributes to the anti‐tumor efficacy of anti‐PD‐1 by activating CD4+ T, CD8+ T, and NK cells." (PMID 37097643, 2023). "Research shows that the tumor endothelium downregulates the expression of endothelial adhesion molecules (EAM) such as ICAM1/2, VCAM1, E-selectin, and CD34." (PMID 37056346, 2023). "ICAM1 on tumor cells facilitates their adhesion to leukocytes, which subsequently bind to the endothelium, therefore supporting metastasis." (PMID 36871040, 2023). "Activation of CAR T cells induces them to release IFN-γ, which can stimulate the expression of ICAM-1 in tumor cells." (PMID 37237555, 2023). "ICAM1 is known to play a role in the tumor-NK cell interactions, needed for effective NK cytotoxicity." (PMID 36656721, 2023). "Our findings renovate that ICAM1 on tumor cells orchestrates anti-tumor immune response, especially for adaptive immunity." (PMID 36871040, 2023). "In SCC, Dsg2 promotes tumor development and progression by increasing the production of ICAM-1 and IL-8, which inhibit leukocyte binding and promote inflammation and, ultimately, tumor progression." (PMID 37173918, 2023). "In this study, we show that tumor-derived GDF-15 inhibits the LFA-1/ICAM-1 axis in T cells and T cell migration into tumor tissue." (PMID 37474523, 2023). "Meanwhile, autocrine IFNs mediated CXCL10 and ICAM-1 expression in RT-treated tumors, which is potential to enhance LFA-1-ICAM-1 interaction for further activating anti-tumor CD8+ T cells." (PMID 36688994, 2023). "The expression of ICAM‐1 reveals the correlation between the immune system and tumour growth, even though the pro‐ or anti‐tumour immune roles of ICAM‐1 are controversial." (PMID 37082943, 2023). "Statistical analysis confirmed that fluorescent signals of ICAM1-Cy5.5 and ICAM1-MMAE-Cy5.5 accumulated at the tumor site were more than 2-fold higher than that of IgG-Cy5.5." (PMID 37717087, 2023). "Treatment with anti‐PD‐1 and sICAM‐1 enhanced the anti‐tumor effects in anti‐PD‐1‐sensitive and ‐resistant mouse cancer models, indicating that ICAM‐1 restored anti‐PD‐1 efficacy." (PMID 37097643, 2023). "For example, ICAM1-targeted CAR T cells in combination with PD-1 blockade demonstrated an improved ability to eradicate ICAM1-expressing target tumour cells compared to CAR T treatment alone." (PMID 37635247, 2023). "Further reverse translational studies using murine syngeneic tumor models reveal that soluble ICAM‐1 (sICAM‐1) is a key molecule that increases the efficacy of anti‐PD‐1 via activation of cytotoxic T cells." (PMID 37097643, 2023). "As an adhesion molecule and signal receptor, ICAM1 is involved in inflammation and wound healing, and also regulates the survival and spread of tumor cells." (PMID 37717087, 2023). "Decreased ICAM1 was observed in more than 80% of LKB1-mutated tumor samples examined, whereas 80% of LKB1-WT specimens showed intensified ICAM1 staining." (PMID 36871040, 2023).
tumor (continued). "IHC staining of tumor tissue displayed reduced ICAM1 expression and CD8+ T-cell infiltration in LLC1-shLkb1-sgIcam1 tumors compared with LLC1-shLkb1-sgCon tumors after palbociclib treatment or combination therapy." (PMID 36871040, 2023). "IHC of human NSCLC tissue arrays showed that the number of CD8-positive cells was positively correlated with ICAM1 expression on tumor cells (Pearson correlation: r = 0.642, p < 0.0001)." (PMID 36871040, 2023). "Specifically, the tumor-killing cytotoxicity of CAR-T is attenuated in antibody-blocked ICAM1 or ICAM1 knockout tumor models." (PMID 38115906, 2023). "IL-17A addition into tumor cell-derived medium significantly reduced the ICAM-1 expression of both murine (C166 cells) and human (HUVECs) vascularly endothelial cells." (PMID 37605139, 2023). "Further examination revealed that tumor cells employed ICAM1 to connect with endothelial or tumor cells to form cell clusters." (PMID 36632469, 2023). "Interactions with circulating neutrophils can increase tumor cell retention and extravasation via neutrophil CD11b, endothelial ICAM-1; and the success of these interactions decline with increasing shear rates resulting from blood flow." (PMID 38020912, 2023). "In comparison with control groups, the CCA tumor growth rate in the ICAM1 ADC-treated groups showed a significantly decreasing trend." (PMID 37717087, 2023). "Tumor endothelial cells also show reduced expression of leukocyte binding molecules, including ICAM-1 and 2, VCAM-1, E-selectin and CD34, leading to reduced response to inflammatory signals and defective recruitment of immune cells." (PMID 37234993, 2023). "Top gene hits identified through both screens involved in for example TNFα signaling were CFLAR, MAPK1, RIPK1, TNFRSF1A, and ICAM1, highlighting their role in regulating tumor sensitivity to TNF-α-induced cell death." (PMID 37732732, 2023). "ICAM-1 can promote tumor cell/T-cell interaction and T-cell activation, and the knockdown of EWS-FLI1 upregulates ICAM-1 expression and leads to the upregulation of PD-L1 and PD-L2, both proteins that inhibit the activity of T-cells." (PMID 37627063, 2023). "Neutrophil-tumor cell interactions are mediated by integrins on neutrophils binding to intercellular adhesion molecule 1 (ICAM-1) on tumor cells." (PMID 37158964, 2023). "The role of ICAM-1 in the immune response is well documented but its role in regulating anti-tumor response and tumor-CTL interaction remains elusive." (PMID 37732732, 2023). "Next, ICAM‐1 levels in tumor tissues of anti‐PD‐1‐responsive and ‐resistant mouse models were analyzed." (PMID 37097643, 2023). "The CX3CL1-CX3CR1 axis was found to be essential for promoting ICAM-1 regulation of tumor metastasis." (PMID 37875556, 2023). "ICAM1 in association with macrophage 1 antigen (MAC-1), CD11b/CD18, lymphocyte function-associated antigen (LFA)-1, CD11a/CD18, and CD11b/CD18 promotes tumor metastasis by activating the immune system and enhancing cell signaling and inflammatory responses." (PMID 37671167, 2023). "Binding of LFA-1 to its ligand ICAM-1 expressed by endothelial cells, APCs and tumor cells, facilitates endothelium adhesion, prolonged contact with APCs, and tumor cell binding." (PMID 37122741, 2023). "ICAM‐1 expression in tumor tissues was elevated in wild‐type CT26 treated with anti‐PD‐1 compared to the control group; however, no significant change was observed in ICAM‐1‐depleted CT26." (PMID 37097643, 2023). "They showed that lower ICAM-1 expression permits polarization of macrophages to a tumor-favoring M2 phenotype, increasing the chance of metastasis." (PMID 37237555, 2023). "CAV1 and ICAM1 upregulation under oxidative stress is also involved in tumor proliferation and migration, as well as chronic lung inflammation." (PMID 37131205, 2023). "A major utility of immunodeficient models, on the other hand, is that they allow discrimination of the functions of ICAM-1 in tumor cells from its functions in the immune system." (PMID 37237555, 2023).